IGLL5 (immunoglobulin lambda like polypeptide 5)
Synonyms: IGLV; VL-MAR
Tractability: Antibody: UniProt places it where antibodies can reach, with medium confidence; UniProt predicts a signal peptide or a membrane-spanning region; its Gene Ontology location is reachable by antibodies, with medium confidence. PROTAC: ubiquitination databases record sites on it; its protein half-life has been measured.
Gene: Protein-coding gene on chromosome 22 (22,887,780 to 22,896,111, forward strand). Ensembl gene ENSG00000254709.
Subcellular location: Secreted
Gene Ontology:
Molecular function: antigen binding
Biological process: immunoglobulin mediated immune response
Cellular component: extracellular exosome; IgG immunoglobulin complex; extracellular region
Genetic constraint (gnomAD): Loss-of-function variants: 30 observed, 19.3 expected, observed/expected ratio (o/e) 1.55, 90% interval 1.15 to 1.92. The synonymous counts are far from expectation, so gnomAD's model fits this gene poorly and the ratio says little. Missense variants: 471 observed, 256.68 expected, observed/expected ratio (o/e) 1.84, 90% interval 1.7 to 1.96. Synonymous variants: 202 observed, 110.58 expected, observed/expected ratio (o/e) 1.83, 90% interval 1.62 to 1.97.
Homologues: Orthologues: rabbit IGLL1 (48% identical), mouse Iglc1 (35% identical), rat Iglc1 (35% identical), mouse Iglc4 (32% identical), mouse Iglc3 (32% identical), mouse Iglc2 (31% identical). Paralogues in human: IGLL1 (61% identical), IGLC1 (49% identical), IGLC2 (47% identical), IGLC3 (47% identical), IGLC7 (46% identical), IGHG1 (22% identical), IGHG2 (22% identical), IGHG3 (22% identical), IGHA2 (21% identical), IGHG4 (21% identical), IGHM (21% identical), IGHA1 (20% identical), and 65 more.